RNU6-478P (RNA, U6 small nuclear 478, pseudogene)
Gene: Small nuclear RNA gene on chromosome 10 (83,067,962 to 83,068,071, reverse strand). Ensembl gene ENSG00000200774.
Homologues: Orthologues: chimpanzee U6 (98% identical), macaque U6 (89% identical), guinea pig U6 (77% identical), rabbit U6 (68% identical), dog U6 (65% identical). Paralogues in human: RNU6-1145P (84% identical), RNU6-1316P (84% identical), RNU6-29P (83% identical), RNU6-38P (83% identical), RNU6-20P (82% identical), RNU6-35P (82% identical), RNU6-393P (82% identical), RNU6-434P (82% identical), RNU6-1075P (81% identical), RNU6-1189P (81% identical), RNU6-1336P (81% identical), RNU6-16P (81% identical), and 1285 more.